IL6 (interleukin 6)
Diseases named in the same sentence as IL6 in open-access papers (continued):
Sharing a sentence is not in itself a finding about the gene and the disease.
tumor (continued). "Granulocyte–macrophage colony-stimulating factor and IL-6 expression were upregulated in Stat3-deficient tumours only at the latest time point." (PMID 25734337, 2015). "Further, IL-6 can also promote the generation of tumor-associated macrophages (TAM) that support tumor metastasis." (PMID 26258068, 2015). "In agreement with the effects seen in vitro, loss of COX-2 expression by tumor cells led to a significant decrease in expression of IL-6 or CXCL1 in vivo." (PMID 26343581, 2015). "Collectively, these data suggest that anti-tumor activity and pro-apoptotic effect of icaritin on human U266 cells is associated with the mechanism involved in targeting IL-6/JAK2/STAT3 signaling pathway." (PMID 25865044, 2015). "This points to a direct correlation between IL-6 levels in tumor-associated endothelial cells and the tumorigenicity of CSC." (PMID 25590298, 2015). "We focused on the secretion of EGF, HGF and IL6, because these soluble factors have been associated with an important role in tumor progression, resistance and inflammation." (PMID 26053043, 2015). "Anti-IL-6 receptor monoclonal antibody neutralizes tumor-derived IL-6 and thus suppresses expansion of cancer-associated MDSCs." (PMID 26078490, 2015). "IL-6 is an important mediator involved in the cross talk between cancer-associated fibroblasts (CAFs) and tumor cells." (PMID 26347589, 2015). "Previous literature documents the production IL-6 (a cytokine associated with the development of chemo-resistance) by macrophages under the influence of tumor-derived factors." (PMID 26608647, 2015). "The multifunctional oncoprotein Y-box binding protein-1 (YB-1) and the pleiotropic cytokine interleukin 6 (IL-6) have both been implicated in tumor cell metastasis and EMT, but via distinct pathways." (PMID 26512918, 2015). "To explore the mechanism underlying the functional interplay of NOX4 and IL-6 in enhancing A549 tumor growth and survival of NSCLC cells in vivo, we sought to determine the reciprocal activation between NOX4/Akt and IL-6/STAT3 signalings in vivo." (PMID 25504436, 2015). "Our present study revealed that upregulation of PAK1 kinase activity conferred stem-like phenotype via NF-κB/IL-6 activation in vitro and in vivo that defines a novel potential mechanism underlying tumor metastasis and sunitinib resistance in RCC patients." (PMID 25675297, 2015). "There is evidence that IL-6 is implicated in promoting tumour growth metastasis and participates in the development of cancer cachexia." (PMID 26508818, 2015). "Tumour presence has been associated with elevated serum IL-6 and TNF-α in mice bearing the Lewis lung carcinoma or B16 melanoma cells compared to controls." (PMID 26508820, 2015). "Cancer cells induce NFkB signalling in tumour-associated macrophages (TAMs), triggering their IL6 secretion, which in turn stimulates the neoplastic proliferation via STAT3 activation." (PMID 25915429, 2015). "As one of the most important members of the MAPK family, p38 had been reported to exert impacts on the process of tumor generation through its effects on the activities of some inflammation associated interleukins, including the pivotal IL-6 factor." (PMID 25826372, 2015). "They found an association of higher IL-6 with tumor invasion and metastasis with the significant difference in OS." (PMID 26693355, 2015). "Inflammation was evaluated by measuring C-reactive protein, a non-specific acute phase protein that serves as a surrogate for interleukin 6, an inflammatory cytokine associated with angiogenesis, tumour growth and metastases." (PMID 26157638, 2015). "Here, the authors demonstrate that this phenomenon is at least partially due to an overproduction of IL-6 caused by ageing and its inhibitory effect on Th1 differentiation of tumour-specific CD4 T cells." (PMID 25850032, 2015).
tumor (continued). "Studies have shown that IL-6 level is significantly associated with tumor invasion level, disease severity, and metastasis." (PMID 26082901, 2015). "IL-11 belongs to IL-6 cytokine family, which consisted of IL-6, IL-11, IL-27, IL-30, IL-31, oncostatin M, and others, and it can be secreted by cancer-associated fibroblasts, myeloid cells, and tumor cell itself." (PMID 25929737, 2015). "Our data show the upregulation of the tumor-associated antigens CEACAM5/6 by trans-signaling of the pro-inflammatory cytokine IL-6." (PMID 26673628, 2015). "Inflammation within the PC microenvironment has been mechanistically linked to tumor progression and chemoresistance through NF-κB, IL-6, toll-like receptor and TGF-β signaling pathways." (PMID 26498838, 2015). "Ligation of DC-SIGN and tumor-associated Le glycans also strongly enhance LPS-induced anti-inflammatory cytokine secretions of IL-6 and IL-10 by monocyte-derived DCs." (PMID 26379663, 2015). "Conversely, IL-6 has been associated with proliferative signaling in both tumor cells and immune cells via binding to glycoprotein 130 and subsequent signal transducer and activator of transcription (STAT) 3 signaling." (PMID 26307977, 2015). "Our results are in agreement with previous findings showing that the release of IL-6 by mesenchymal cancer cells and tumor-associated macrophages was able to induce EMT and macrophage polarization toward a pro-tumoral M2 profile." (PMID 26452030, 2015). "In this context, it is important to note that the activation of the IL6 pathway has been implicated in the resistance to Trastuzumab (anti-Her2) in PTEN-deficient tumor cells." (PMID 26053043, 2015). "In the 39 patients who underwent preoperative chemoradiotherapy for locally advanced OSCC, the association of IL-6 expression in the cancer cells with histologic tumor response in the resected specimens was further examined." (PMID 25761055, 2015). "In this regard, serum IL-6 has shown significant association with tumor burden, clinical disease status, and survival, as well as prognostic value, in EOC." (PMID 26282935, 2015). "In the tumor microenvironment, tumor cell-derived factors (e.g., TGF-β1, IL-10, IL-6) induce the polarization of macrophages into tumor-associated macrophages (TAMs) with pro- or anti-tumor phenotypes." (PMID 31557983, 2015). "Circulating IL-6 levels are positively associated to a clinical tumour stage, lymph node infiltration, and the number of distant metastases in BC patients." (PMID 25705130, 2015). "Tumor-associated inflammatory cytokines, such as IL-6 and TNF-α, are likely to regulate cancer cells in the tumor microenvironment." (PMID 24396476, 2014). "The most pronounced effect of IL-15 loss on tumor-associated cytokine protein was on IL-6, which was reduced an average of 7-fold in IL-15−/− Tax tumors." (PMID 24416335, 2014). "In the initiation stage of CAC, IL-6 acts as a tumor promoter by binding to its gp130-associated receptor and activated Stat3 signal pathway, which is the major protumorigenic effector for IL-6." (PMID 25093140, 2014). "Studies showed that, during colitis-associated colonic tumorigenesis, IL-6 in the intestinal lamina propria enhances STAT3-dependent proliferation of tumor-initiating cells and protection of premalignant intestinal epithelial cells from apoptosis." (PMID 24757565, 2014). "Of these cytokines, proinflammatory cytokines, including TNF-a and IL-6, have been demonstrated to activate the NFkB pathway which is then associated with tumor progression." (PMID 24732966, 2014). "The present study indicates that progression of androgen-dependent LNCaP tumors to androgen independence is associated with an increase in IL-6 and that treatment with atorvastatin and celecoxib inhibited the increased tumor level of IL-6." (PMID 24296978, 2014). "Taken together, these results demonstrated that downregulation of IL-6 in tumor-associated endothelial cells is sufficient to inhibit tumor growth." (PMID 24533454, 2014).
tumor (continued). "The role of TNF and IL-6 as master regulators of tumour-associated inflammation and tumourigenesis makes them attractive targets for adjuvant treatment in cancer." (PMID 24667059, 2014). "Clinical studies have demonstrated that increased serum IL-6 concentrations are associated with advanced tumor stages and short survival in patients with solid neoplasms." (PMID 24886605, 2014). "In search for a possible mechanism for the activation of the STAT3 signaling pathway, we observed that silencing interleukin (IL)-6 in tumor-associated endothelial cells inhibited STAT3 phosphorylation in tumor cells." (PMID 24533454, 2014). "High serum levels of IL-6 have been shown in many different cancer types, and positive associations with tumour stage, size and disease progression have been reported." (PMID 24884871, 2014). "The main finding of the present study was that IL6 genotype was strongly associated with early events among patients with ER-negative tumours, particularly among radiotherapy-treated patients, and among chemotherapy-treated patients irrespective of ER-status." (PMID 25305747, 2014). "In a chronic inflammatory process, cytokines such as TNF-α and IL-6 induce the generation of free radicals that can damage DNA, potentially causing mutations that lead to tumor initiation." (PMID 24901008, 2014). "SYD reduced the expression levels of serum interleukin 1β, interleukin-6, tumor necrosis factor α, tumor-associated macrophages, and p65." (PMID 24766737, 2014). "Stat3 has been shown to maintain constitutive NF-κb activation in tumor-associated myeloid cells, and several inflammatory factors encoded by NF-κb target genes, notably IL-6 released by TAMs, are important Stat3 activators." (PMID 24723924, 2014). "IL-6 is known to cause the loss of lean body weight in CT-26 tumor-bearing cachectic mice by inducing proteolytic pathways." (PMID 24963216, 2014). "The main finding was that IL6 genotype was strongly associated with early events among patients with ER-negative tumours, especially in radiotherapy-treated patients, and among chemotherapy-treated patients irrespective of ER-status." (PMID 25305747, 2014). "This positive feedback loop was found in both tumor cells and tumor-associated stromal cells, and the IL-6 produced by these two types of cells mediates the crosstalk between them, and enables a persistent activation of STAT3 in both cell types." (PMID 24995504, 2014). "It is thought that IL-10 deficiency leads to elevated levels of TNF-α, IL-6, and IL-17, which in turn allow persistence of chronic inflammation thus promoting tumor growth." (PMID 24639678, 2014). "In animal models of cancer cachexia, mitochondrial content and biogenesis are reduced with increased levels of IL-6 during the progression of the condition whereas inhibition of IL-6 activity attenuates tumor-induced loss of skeletal muscle." (PMID 23835416, 2013). "Some other reports indicated inhibited tumor growth in IL-17 deficiency mice due to the increased myeloid-derived suppressor cells (MDSCs) infiltration and IL-6 production in tumors." (PMID 24453427, 2013). "In the present study, dietary iron enhanced colonic IL-6/IL-11-Stat3 signaling and promoted colonic inflammation and tumor development in a DSS mouse model of inflammation-associated colorectal tumorigenesis." (PMID 24223168, 2013). "Freshly harvested B16 tumor cells from wild-type mice produced relatively high level of IL-6, which was reduced with IL-17 deficiency." (PMID 24453427, 2013). "IL-6 signaling has been implicated in the regulation of tumor growth and metastatic spread in different cancers." (PMID 23561329, 2013). "Here, we have shown that photo-oxidative (due to ROS induction) tumor cells and the eventual upregulation of IL-6-facilitated tumor cell death have underpinned the association of certain primary apoptotic mediators with inhibition of tumor growth." (PMID 23807226, 2013).
tumor (continued). "IL-6 deficiency has attenuated tumor development in a colitis-associated carcinogenesis model, demonstrating its role in inflammation-associated tumor promotion." (PMID 23593346, 2013). "In previous studies, SNP −174 G>C in IL-6 promoter has been associated to diverse tumors but the reported results are contradictory regarding the genotype associated to tumor progression." (PMID 24204677, 2013). "Tumor-associated fibroblasts were found to secret IL-6 and the conditioned medium harvested from the fibroblasts also induced STAT3 activation in NPC cells." (PMID 24380387, 2013). "In contrast, treatment with QYHJ inhibited cancer-related inflammation in tumors by decreasing infiltration of tumor-associated macrophages and IL-6 production, thus preventing cell invasion and metastasis." (PMID 23922983, 2013). "Using a xenograft tumor model, our data demonstrated that IL-6 level positively linked with angiogenesis and STAT3 activation." (PMID 23637926, 2013). "To investigate if tumor-derived IL-6 is directly linked to changes in CRH expression under in vivo conditions, we inoculated intravenously control B16-F10 cells and B16-F10 cells transfected with siRNA specific for IL-6 (B16-F10/IL-6-siRNA)." (PMID 23517603, 2013). "MCP-1 or MIP-1 loss significantly promotes primary tumor growth and lung metastasis by inhibiting IL-6, TNF-α and TGF-β expression." (PMID 23426399, 2013). "IL-6, which is encoded by an NF-κB target gene, is proposed to be one of these tumor growth factors." (PMID 23117246, 2013). "High expression of PI3K, p-Akt, IL-6, TNFα and VEGF were significantly associated with the higher histological grade, and high expression of PI3K, p-Akt and IL-6 were significantly associated with tumor recurrence." (PMID 23688241, 2013). "Second, tumor growth causes tissue inflammation in the tumor microenvironment by increasing the production of inflammatory proteins, particularly IL-6." (PMID 24255664, 2013). "Mouse studies demonstrated that IL-6 is important for both tumor development and growth in colitis associated cancer, with IL-6 promoting both proliferation and survival of intestinal epithelial cells via the activation of the transcription factor STAT3." (PMID 23987103, 2013). "IL-6 has also been proposed as a cause of natural killer cell dysfunctions, thus potentially representing a mechanism of tumor escape from immune surveillance." (PMID 27335826, 2013). "Stimulation of BM myeloid cells by crosslinking CD79a induced the secretion of several cytokines associated with tumor and metastasis promotion, in particular IL-6, RANTES, TNFR-II, CXCL16 and CCL22." (PMID 24146823, 2013). "The results indicated that QYHJ inhibited cancer-related inflammation in tumors by decreasing infiltration of tumor-associated macrophages and IL-6 production, which ultimately decreased EMT and cell invasion." (PMID 23922983, 2013). "Down regulation of tumor IL-6 expression in mice bearing B16-F10/IL-6-siRNA metastases associated with a decrease in circulating IL-6 levels." (PMID 23517603, 2013). "In summary, our results provide evidence that IL-6 deficiency promotes lung tumorigenesis, but suppresses tumor progression and elongates survival in vivo." (PMID 24260500, 2013). "P2Et fraction exerts its activity on the primary tumor, reduces cell migration to distant organs, and implies the involvement of tumor microenvironment-associated mechanisms in the drop in IL-6 serum levels." (PMID 23552194, 2013). "Taken together, virally encoded hyper-IL-6 was efficiently and functionally secreted from infected tumor cells." (PMID 22236378, 2012). "In male OSCC patients, high IL6 expression in tumor cells was associated with poor prognosis (P = 0.025) and a 1.454-fold higher death risk, as determined by Cox regression." (PMID 23185547, 2012). "The model of subcutaneous tumor implantation also shows an increase in circulating IL-6 levels associated with muscle and total body weight loss." (PMID 22428048, 2012).
tumor (continued). "As to this case, inhibition of STAT3 caused decreased production of IL-6.The activation of STAT3 pathway has been studied in patients’ tumor tissue samples." (PMID 22662257, 2012). "Certain cytokines (e.g., IL-6 and CSF-1) can influence the phenotype and the function of tumor-associated macrophages and indirectly stimulate tumor invasiveness and angiogenesis." (PMID 23024650, 2012). "Recently, adhesion of MM cells was linked to enhanced STAT-3 mediated IL-6 signaling, supporting further the survival and proliferation of the tumor." (PMID 22558078, 2012). "IL-10 in combination with IL-6 can lead to upregulation of molecules in TAMs, which are implicated in suppression of tumour-specific T cell immunity." (PMID 22778767, 2012). "Deregulation of MYC, vascular endothelial growth factor A, and interleukin 6 has been reported to be strongly associated with tumor growth and metastatic invasion." (PMID 23049873, 2012). "The association between tumor IL6 expression and clinical parameters in 337 oral squamous cell cancer (OSCC) patients." (PMID 23185547, 2012). "High IL6 expression in tumor cells was significantly associated OSCC patient characteristics including female gender (P<0.001), high lymph node metastatic rate (P = 0.007), and poor tumor differentiation (P = 0.008)." (PMID 23185547, 2012). "Several inflammatory interleukins, including IL-1, IL-6, IL-8, and IL-18, are associated to tumour genesis." (PMID 23905066, 2012). "These included genes known to be expressed by microglia (CCL8, SPP1, IRF7, IL1RAP), macrophages (IL1RN, SPP1, PDPN, IL1RAP, MDK, TFRC, HRH4), and tumor-associated macrophages (IL6, SPP1)." (PMID 22937035, 2012). "Senescent fibroblasts secrete more than 40 factors associated with intercellular signaling, including IL-6 and IL-8, many of which have been implicated in tumor progression." (PMID 23216814, 2012). "Recently, elevations in serum level of interleukin 6 (IL-6) and expression of Twist in tumor samples were found to be associated with poor clinical outcomes in multiple types of cancer, including SCCHN." (PMID 21559372, 2011). "In a mouse tumor model, the IL-1R-deficient mouse has a delayed accumulation of MDSCs, which can be partially restored by IL-6." (PMID 21394214, 2011). "Next, we probed TC1 cells using qPCR for transcription of two pro-inflammatory cytokines, Il-6 and Il-23p19, both of which have been implicated in tumor progression." (PMID 21649922, 2011). "Tumor-associated inflammatory cytokines such as IL-6 and tumor necrosis factor (TNF)-α probably regulate Th17 cells in the tumor microenvironment of ovarian cancer mouse model." (PMID 21943203, 2011). "Tumour invasion and the presence of distant metastasis is associated with higher IL-6 levels (P = 0.001, P = 0.009)." (PMID 21294915, 2011). "Biomarker analyses of HCC patients treated with sunitinib showed a correlation between decreased levels of IL-6 and soluble c-KIT and a delayed tumor progression; vice versa elevated levels of IL-6 and c-KIT were associated with an unfavorable disease course." (PMID 22072937, 2011). "Tumor growth and lung metastasis were intensified in IL-17 deficient mice whereas in vitro TGF-β and IL-6 polarized Th17 cells induced tumor regression." (PMID 21943203, 2011). "HCC development is dependent on enhanced production of the tumor promoting cytokines such as IL-6 which causes hepatic inflammation and activation of the oncogenic transcription factor STAT3." (PMID 22032643, 2011). "Gene-expression analysis of bone metastases demonstrated that GSI-treated mice displayed a downregulation of Notch target genes in the tumour-associated stromal compartment, including a decrease in IL-6 levels." (PMID 22075946, 2011). "In human ovarian cancer, tumor-associated regulatory T (Treg) cells trigger macrophages to produce IL-6 and IL-10, and these cytokines in turn stimulate APCs to express B7-H4 in an autocrine and/or paracrine manner." (PMID 22013483, 2011).